IL1B (interleukin 1 beta)
Diseases named in the same sentence as IL1B in open-access papers (continued):
Sharing a sentence is not in itself a finding about the gene and the disease.
psoriasis (continued). "More importantly, protein levels of N-GSDMD and IL-1β (a key secretory cytokine through GSDMD-mediated pyroptosis) were significantly increased in epidermal lysates of skin lesion tissue samples from patients with psoriasis but not in epidermal lysates from normal skin tissue samples." (PMID 37673869, 2023). "Urate crystals activate the NLR family pyrin domain-containing three inflammasomes in macrophages, resulting in the production of active IL-1β and IL-18, and promote the production of TNF-α in monocytes, indicating that UA might increase the levels of inflammatory cytokines promoting psoriasis." (PMID 36902720, 2023). "In addition, it was reported that LL-37 might activate monocytes (P2 × 7 receptor), leading to inflammasome activation and IL-1β production, whereas DNA bound by LL-37 did not enhance Il-1β secretion in psoriasis." (PMID 35163760, 2022). "Furthermore, IL-1β stimulation of NHEKs was found to induce upregulation of the mRNA and protein levels of pro-inflammatory cytokines, chemokines and antibiotic peptides including IL-36γ, CXCL1, CXCL2, CCL20, S100A7, S100A8 and S100A9, which are closely related to the pathogenesis of psoriasis." (PMID 32194991, 2020). "However, only the HLADRII+CD206+ ATM subset demonstrated a statistically significant difference in IL-1β (40.3% in psoriasis versus 19.6% in controls, p = 0.047), but not IL-8 (62.5% in psoriasis versus 45.7% in controls, p = 0.117), production between psoriatic and control adipose tissue." (PMID 25224267, 2014). "Salivary interleukins, including IL-1β, IL-6, TNF-α, and IL-17, offer significant results as non-invasive biomarkers for early detection, severity assessment, and treatment monitoring of psoriasis, effectively reflecting systemic inflammation." (PMID 40731810, 2025). "IMQ rapidly triggers psoriasis development by activating TLR7 on dendritic cells to produce pro-inflammatory cytokines, including IL-23 and IL-1β, without directly providing specific antigens to be presented through MHCI and MHCII." (PMID 37594540, 2023). "In psoriasis biopsy, the expression of NLRP3, caspase-1, and IL-1β was significantly upregulated compared to non-lesional psoriatic skin." (PMID 34707607, 2021). "Neutrophils are the dominant skin infiltrating immune cells during psoriasis development; however, MKP-1 activity in neutrophils was not required for the Il1b expression upon stimulation." (PMID 29619028, 2018). "In FFA4 KO mice, the levels of inflammatory TH23/TH17 axis cytokines (IL-17A, IL-22 and IL-23) and TH1 cytokines (IL-1β, IFN-γ and TNF-α) in the lymph nodes were also increased after psoriasis induction; however, Compound A treatment did not suppress the cytokine levels." (PMID 35562873, 2022). "However, in the uninvolved skin of patients with early-onset psoriasis, the ability of LCs to migrate in response to topical exposure to the contact allergen diphenylcyclopropenone, and to the cytokines TNF-α and IL-1β, is absent." (PMID 21933242, 2012).
type 2 diabetes (406 papers, 2008 to 2026). "We previously showed that hypomethylation of the IL1RN and NFKB1 gene promoters is associated with dysregulation of the IL-1β/IL-1Ra axis in type 2 diabetes." (PMID 40821781, 2025). "IL-1β, a major pro-inflammatory cytokine, is critically involved in INS signaling alterations; in obese individuals, high IL-1β and IL-6 circulating levels represent an important independent risk for developing type 2 diabetes." (PMID 40940769, 2025). "In particular, previous reports indicate that an age-associated increase in serum concentrations of IL-1β contributes to diseases such as type 2 diabetes, Alzheimer’s disease, and motor dysfunction." (PMID 38839869, 2024). "In the spinal cord, the NLRP3/Casp1/IL-1β inflammasome activation axis is associated with chronic itch in type 2 diabetes and IMQ-induced chronic itch models." (PMID 39867900, 2024). "The concentration of IL-1β is increased in OB humans, with the combination of elevated IL-1β and IL-6 increasing the risk of both type II diabetes and metabolic syndrome." (PMID 39328456, 2024). "Although the exact pathogenesis of PDN is unclear, there was increased secretion of mRNA encoding NLRP3, ASC, IL-1β, and IL-18 in macrophages and peripheral blood monocytes of patients with type 2 diabetes mellitus." (PMID 37106238, 2023). "Testosterone replacement therapy to testosterone-deficient men undergoing type 2 diabetes decreases the synthesis of the proinflammatory cytokines IL-1β, IL-6 and TNF-α in antigen-presenting cells." (PMID 36551196, 2022). "Increased circulating IL-1β levels have been associated with the risk of developing type 2 diabetes, inasmuch as IL-1β contributes to inhibiting β-cell function and destroying β-cell mass and impairs adipocyte insulin signaling." (PMID 34884217, 2021). "Increased blood IL-1β concentrations are associated with the pathogenesis of type 2 diabetes, linking DINCH and MINCH to potential adverse health outcomes." (PMID 34572016, 2021). "Elevated levels of IL-6 and IL-1β in adipose tissue have been reported to contribute to the risk of type 2 diabetes." (PMID 32019160, 2020). "In particular, according to our projection approach, genes TGFB1 and IL1B are good candidates for association with type 2 diabetes." (PMID 31845988, 2020). "It has been shown that increase in the level of IL-1β is a risk factor for the development of type 2 diabetes." (PMID 33061223, 2020). "The elevated mtDNA levels were associated with interleukin-1β (IL-1β) levels in patients with type 2 diabetes." (PMID 30965677, 2019). "Further IL-1β is implicated in various diseases like atherosclerosis, chronic heart failure and type 2 diabetes mellitus (T2DM), which are considered as associated risk factors of PCOS30." (PMID 31308416, 2019). "TNF-α, IL6, MCP1 and IL1-β, were also significantly upregulated (p < 0.05) in PBMCs from patients with type 2 diabetes, implying an acquisition state of senescence-associated secretory phenotype." (PMID 30139387, 2018). "Interleukin-1beta (IL1B) has been associated with loss of beta-cell mass in type-II diabetes (TIID)." (PMID 27749914, 2016). "In animal models for type 2 diabetes, characterization of the increased infiltrating islet-associated macrophages indicated a pro-inflammatory M1 phenotype, with production of IL-1β and TNFα." (PMID 25956355, 2015). "Calorie restriction in mice and patients with type 2 diabetes who lose weight show reduced IL–1β and NLRP3 mRNA in adipose tissue, and this is associated with a decrease in their pro-inflammatory profile and insulin sensitivity." (PMID 26437377, 2015). "Individuals with combined elevated plasma levels of IL-1β and IL-6 are at increased risk for developing type 2 diabetes, but even mild weight loss in obese patients resulted in a 45% decrease in serum IL-1β levels over a three-year study period." (PMID 25403235, 2014).
type 2 diabetes (continued). "CAD patients with MS and type 2 diabetes were treated with pioglitazone, and this therapy was associated with decreased IL-1β, IL-1Ra and IL-10 mRNA expression in EAT." (PMID 24684779, 2014). "IL-1β together with IL-6 concentrations reportedly predicts risk for type 2 diabetes in humans better than either cytokine alone." (PMID 25309773, 2014). "Patients with high level of the circulating IL-1β are associated with greater risk on development of type 2 diabetes." (PMID 25332517, 2014). "An elevation in circulating levels of IL-1β together with IL-6 has been shown to increase the risk of type 2 diabetes." (PMID 24918199, 2014). "Recent animal studies, in-vitro cultures and clinical trials provide evidence that a causative role for IL1B as the primary agonist in the loss of beta-cell mass in type 2 diabetes." (PMID 25221996, 2014). "Several in vitro, in vivo studies and clinical trials provide evidence that supports a causative role of IL-1β in the pathogenesis of type 2 diabetes, and elevation in circulating levels of IL-1β predicts type 2 diabetes when combined with serum IL-6 levels." (PMID 23843683, 2013). "Both IL-1β and IL-6 are known to be regulated in this manner and have been implicated in the pathogenesis of IR and progression to overt type-2 diabetes." (PMID 23844177, 2013). "On bivariate analysis, IL-6, hs-CRP, leptin and γGT were positively associated with increased risk of type 2 diabetes; IL-1β and adiponectin were inversely associated with type 2 diabetes risk." (PMID 23251619, 2012). "Pro-inflammatory cytokines (PIC), and in particular IL-1β, are thought to be important pathogenic effectors responsible for the induction of β-cell dysfunction and apoptosis in both type 1 and type 2 diabetes." (PMID 20585581, 2010). "β-cells are sensitive to cytokines, interleukin-1β (IL-1β) has been associated with β-cell dysfunction and -death in both type 1 and type 2 diabetes." (PMID 19243577, 2009). "Elevated IL-1β is a hallmark of metabolic inflammation and contributes to both impaired insulin secretion and β-cell apoptosis, thereby accelerating the progression of type 2 diabetes." (PMID 40332318, 2025). "Elevated levels of IL-6 and IL-1β have been shown to increase the risk of type 2 diabetes." (PMID 38257186, 2024). "Emerging evidence has indicated that the activation of the NLRP3 inflammasome might lead to the maturation and secretion of IL-1β, which has been implicated in the pathological development of type 2 diabetes and cardiovascular diseases." (PMID 34576117, 2021). "Moreover, IL-1β is linked to inflammation in obesity, type 2 diabetes, insulin-resistance associated entities (e.g., polycystic ovary syndrome), atherosclerosis and other conditions." (PMID 32477265, 2020). "Although IL-1β is known to be involved in the autoimmune process leading to type 1 diabetes, it is also upregulated in the pancreatic islets of diabetic patients and type 2 diabetes animal models, where it causes impaired glucose tolerance." (PMID 32097444, 2020). "Epidemiological studies have reported that levels of pro-inflammatory and inflammatory cytokines such as C-reactive protein (CRP), TNF-α, IL-1β, and IL-6 were elevated in patients with type 2 diabetes and were associated with the development of type 2 diabetes." (PMID 30857216, 2019). "Furthermore, because IL–1β is linked to fatigue in patients with type 2 diabetes and stimulates the hypothalamic-pituitary-adrenal axis, fatigue and cortisol levels were also studied." (PMID 26448147, 2015). "Elevated levels of IL‐1β are a risk factor in the development of type 2 diabetes mellitus (T2D) and increase insulin resistance." (PMID 40671401, 2025). "A clinical study in men with type 2 diabetes who developed partial testosterone deficiency showed testosterone immunosuppressive activity in reducing the synthesis of the proinflammatory cytokines IL-1β, IL-6 and TNF-α, an effect that persists after termination of testosterone treatment." (PMID 36551196, 2022).
type 2 diabetes (continued). "IL1B in particular has previously been associated with coronary heart disease in some genetic backgrounds, which in turn shares many genetic pathways with type 2 diabetes and may share associated genetic variants." (PMID 31845988, 2020). "Additionally, it is now recognized that IL-1β, for which levels were significantly higher in our First Nations sample, is implicated in the disruption of insulin signaling and the severity of type 2 diabetes." (PMID 22768323, 2012). "A prospective study suggested that IL-1β might interact with IL-6, participants with detectable IL-1β levels and elevated IL-6 levels presenting an increased risk to develop type 2 diabetes relative to individuals with undetectable IL-1β levels and increased IL-6 levels." (PMID 23251619, 2012). "This was initially observed in isolated human pancreatic islets, along with increased expression of IL-1β in islets from individuals with type 2 diabetes." (PMID 39496966, 2025). "TNF-α, in particular, impairs insulin signaling by promoting serine phosphorylation of IRS-1, while IL-1β exacerbates pancreatic β-cell dysfunction and contributes to the development of type 2 diabetes." (PMID 40867531, 2025). "TNF-alpha and IL-1β, key pro-inflammatory cytokines, play significant roles in the dysfunction of cells within the islets of Langerhans in type 2 diabetes." (PMID 40182806, 2025). "This study aims to evaluate the association between glycemic control, inflammatory markers (IL-1β, IL-6, MMP-8), and periodontal health in patients with type 1 and type 2 diabetes." (PMID 40283677, 2025). "The cytokine IL-1ra antagonizes the inflammatory effects of IL-1β, halting a key pathway in the development of type 2 diabetes." (PMID 40145019, 2025). "Vitamin D and calcium supplementation through a drinkable yogurt has been associated with a decrease in serum levels of IL-1β and TNF-α in patients with type II diabetes mellitus." (PMID 41141350, 2025). "In multivariable analysis, caspase-1 upregulation was independently associated with STEMI presentation and low-density lipoprotein-cholesterol, and IL-1β with type 2 diabetes." (PMID 41598157, 2025). "Another study showed that indoleacrylic acid (an indole derivative) alleviates type 2 diabetes by activating the aryl hydrocarbon receptor (AhR), which reduces IL-1β, IL-6, and TNF-α levels." (PMID 41156481, 2025). "Later, increased numbers of islet macrophages were identified in individuals with type 2 diabetes, leading to the suggestion that biologically relevant IL-1β is produced by macrophages." (PMID 39496966, 2025). "Studies with these antibodies have confirmed the benefit of antagonising IL-1β in type 2 diabetes, with a placebo-corrected reduction in HbA1c of up to 0.9%." (PMID 39496966, 2025). "IL-1β plays a central role in the progressive decline of pancreatic β-cell function in both type 1 and type 2 diabetes." (PMID 40943225, 2025). "The detection of IL-1β and identification of increased numbers of islet macrophages in human type 2 diabetes and animal models of type 2 diabetes made it conceivable that insulitis plays a role in this condition." (PMID 39496966, 2025). "IL-1β plays a pivotal role in both type 1 and type 2 diabetes by mediating immune dysregulation, β-cell dysfunction, and chronic inflammatory responses." (PMID 40804870, 2025). "The results indicated that women in the DD group had significantly higher levels of IL-1β and leptin compared to the CN group (p < 0.05); however, this significance was lost upon adjustment to type 2 diabetes diagnosis." (PMID 40699752, 2025). "Later, in the context of type 2 diabetes, elevated glucose levels were shown to induce IL-1β production." (PMID 39496966, 2025). "Danggui Buxue decoction (DBD) significantly reduced the levels of TNF-α, IL-1β in serum from GK rats with type 2 diabetes." (PMID 39711801, 2024).
type 2 diabetes (continued). "In the field of type 2 diabetes, blockade of IL-1β with IL-1 receptor antagonists reduced inflammation and improved and/or prevented diabetes in a rat model of type 2 diabetes, high-fat diet-fed mice and in individuals with type 2 diabetes." (PMID 37924378, 2024). "Engaging in aerobic exercise can improve IR and reduce the expression of NLRP3 and IL-1β in individuals with type 2 diabetes in aortic tissue, suggesting its positive impact on IR by inhibiting NLRP3 inflammasome." (PMID 38681198, 2024). "The activation of NLRP3 contributes to a higher expression of IL-1β, and IL-1β is a key cytokine in the etiology of type 2 diabetes." (PMID 36875140, 2023). "TNFα and IL1β have been independently pursued as therapeutic targets in clinical trials for type 2 diabetes and systemic insulin resistance." (PMID 37400454, 2023). "We found that the expression levels of M1 polarized macrophage-related markers, including IL-1b, IL-6, and Tnf, were significantly enhanced in the peri-implantitis coupled with type II diabetes group." (PMID 37519314, 2023). "Randomised clinical trials have shown that blockade of IL-1β with Anakinra leads to a sustained reduction in systemic inflammation and improvement of Type 2 Diabetes." (PMID 36175539, 2023). "Clinical studies have shown that the NLRP3 pathway is significantly activated and the levels of Caspase1 and IL-1β are significantly increased in obese and type 2 diabetes patients compared to healthy subjects." (PMID 36834674, 2023). "C. papaya reinstated the levels of adipocytokines, antioxidant enzymes and mRNA levels of mTOR, TNF-α, IL-1β, IL-6 and IKKβ in the adipose tissues of type 2 diabetic rats." (PMID 36826001, 2023). "This study found that CK treatment significantly reduced inflammatory factors, including TNF-α, IL-6, and IL-1β, in the liver injury model of type 2 diabetes rats." (PMID 37251340, 2023). "In a clinical study of 48 patients with type 2 diabetes, neutralizing IL-1β specific antibody responses were detected after multiple injections of anti-IL-1β vaccine." (PMID 36405706, 2022). "For the first time, we report the association of HIF-1 activation with the antimicrobial peptide LL-37 and HIF-1 target genes PGK1 and IL-1B in type 2 diabetic patients living at high altitude." (PMID 34651203, 2022). "Studies have shown these genes to be involved in the development of type 2 diabetes, for example, a study showing IL-1β-induced β cell dysfunction." (PMID 35281591, 2022). "A study showed that eight weeks of melatonin supplementation for type 2 diabetes patients significantly reduced the levels of malondialdehyde and IL-1β compared to the control group." (PMID 35937803, 2022). "Obese and type 2 diabetic patients exhibited decreased gene expressions of IL-1β and NLRP3 in sWAT and increased insulin sensitivity after diet intervention or exercise." (PMID 35432210, 2022). "In type 2 diabetes, elevated levels of serum pro-inflammatory cytokines such as IL-1β and IL-6 are predictive disease markers." (PMID 35399956, 2022). "IL-1β contributes to systemic inflammation and the progression of modeled CKD, either type 2 diabetes-induced or adenine diet-induced, as shown by studies utilizing monoclonal anti-IL-1β in mice." (PMID 35806457, 2022). "In fact, IL-1β blocking therapies have been reported to improve glycemia in patients with type 2 diabetes." (PMID 35303833, 2022). "IL-1β is a prominent pro-inflammatory mediator that is also involved in the pathogenesis of type 2 diabetes (T2D) through activation of the NLRP3 inflammasome." (PMID 35056315, 2021). "A recent study, described that almost 20 circulating cytokines such as TNFα, IL-1a, IL-1b, GM-CSF, IL-10, IL-12, etc., are elevated in plasma of type 2 diabetic patients." (PMID 34202017, 2021).